MYOF (myoferlin)
Diseases named in the same sentence as MYOF in open-access papers (continued):
Sharing a sentence is not in itself a finding about the gene and the disease.
normal-tension glaucoma (1 paper, 2018). "Although the SNPs near MYOF and XRCC6P1 did not pass the Bonferroni-corrected threshold of P < 0.0125, rs4918865 was more strongly associated with the high-tension glaucoma (HTG) subset (P = 0.003 for HTG vs. P = 0.37 for normal-tension glaucoma (NTG)) in NEIGHBORHOOD." (PMID 29449654, 2018).
rectal cancer (1 paper, 2025). A primary or metastatic malignant neoplasm that affects the rectum. "Recent studies have shown that MYOF is overexpressed in various cancers, including CRC, and high MYOF expression in rectal cancer is associated with poor clinical prognosis in patients." (PMID 39941891, 2025).
triple-negative breast carcinoma (1 paper, 2022). An invasive breast carcinoma which is negative for expression of estrogen receptor (ER), progesterone receptor (PR), and human epidermal growth factor receptor 2 (HER2). "Assessment of the function of myoferlin in energy metabolism had shown that myoferlin could modulate the cell metabolism between oxidative phosphorylation and glycolysis, and the conversion of saturated to unsaturated fatty acids in triple-negative breast cancer cells (TNBC)." (PMID 36147922, 2022).
cancer (46 papers, 2012 to 2025). A tumor composed of atypical neoplastic, often pleomorphic cells that invade other tissues. "Taken together, this data supports a cell type specific function of myoferlin, as the main function of myoferlin in CAFs is to support COPII vesicle trafficking, while cancer cell myoferlin is predominantly linked to mitochondrial fitness." (PMID 41062852, 2025). "Strikingly, we were unable to find an association of cancer cell myoferlin with overall patient survival." (PMID 41062852, 2025). "They demonstrated that myoferlin depletion in cancer cells leads to exosomes that are functionally deficient and have a significantly reduced ability to induce the migration and proliferation of those cells." (PMID 37893211, 2023). "Myoferlin hyperexpression has been determined as an independent risk factor in developing a subsequent primary malignant tumor in patients with ccRCC." (PMID 35320116, 2022). "High expression of MYOF has been associated with shorter survival in patients with breast, pancreatic, and colorectal cancers." (PMID 36147922, 2022). "MYOF, a membrane protein associated with membrane regeneration and repair, has been reported overexpressed in many cancers and promotes tumour metastasis resulting in poor outcome in patients." (PMID 29164766, 2018). "Myoferlin protein expression has been recently associated with poor prognosis in patients with cancer." (PMID 29179496, 2017). "In the current study we focused on myoferlin, a membrane associated protein, which has recently been demonstrated to be pro-oncogenic in several types of cancer." (PMID 27845903, 2016). "The overexpression of myoferlin in multiple types of cancer suggested that assessment of myoferlin expression may be diagnostic and that this protein could be targeted in cancer treatment." (PMID 36147922, 2022). "Clinically, MYOF overexpression is associated with poor outcome in various cancers." (PMID 31828126, 2019). "Knowing that some cancer cells exhibit mutations in tyrosine kinase receptors, which lead to a constitutive receptor activation triggering the downstream pathways, it can be speculated that myoferlin depletion could impede cell proliferation in these cases." (PMID 31443490, 2019). "MYOF promotes angiogenesis in the tumor microenvironment, is involved in the secretion of exosomes by cancer cells, and enhances the reprogramming of energy metabolism." (PMID 39941891, 2025). "Analysis of the TCGA database revealed that MYOF mRNA expression levels are elevated in various human cancer tissues, including CRC." (PMID 39941891, 2025). "Apatinib, by targeting VEGFR2, promotes the ubiquitination of MYOF, leading to decreased PD-L1 expression, thereby preventing cancer evasion." (PMID 39941891, 2025). "In cancer models, MYOF has been demonstrated to participate in proliferation, invasion, and migration of cancer cells through different mechanisms." (PMID 39941891, 2025). "To date, our knowledge of intracellular vesicle trafficking in PAAD is limited to cancer cells, and a potential importance of vesicle trafficking proteins, such as myoferlin, in pancreatic stromal cells remains to be elucidated." (PMID 41062852, 2025). "This protein is overexpressed in PDAC and its silencing/targeting has been shown to affect cancer cell metabolism, proliferation and migration in vitro; small compounds targeting myoferlin reduced the number of metastases and tumor size in mouse models." (PMID 38368370, 2024). "MYO1E and MYOF, involved in actin-based intracellular trafficking and vesicle transport, respectively, play key roles in cancer cell membrane dynamics and migration." (PMID 39850570, 2024). "After forward search and backward search, we identified a set of five differentially expressed genes (LAMC2, TSPAN1, MYO1E, MYOF, SULF1) in Cancer/Normal that was optimized for diagnostic ability." (PMID 39850570, 2024).
cancer (continued). "Using proteomic analysis, Blomme and colleagues (2016) validated a novel exosomal protein, termed myoferlin, which is related to angiogenesis, metabolism reprogramming, and epithelial–mesenchymal transition in cancer." (PMID 37893211, 2023). "Most of the work has focused on myoferlin, which appears to be the ferlin with the most important role in cancer." (PMID 37538852, 2023). "The study also found that myoferlin knockdown significantly reduced IL-6-mediated tumor cell migration, tumor sphere formation, and the population of cancer stem cells in vitro." (PMID 37538852, 2023). "CCND1, a cell cycle regulator that promotes cellular proliferation and is frequently overexpressed in human cancers, was previously identified by us and others as a central gene whose expression is upregulated in F compared with both MyoF and MyoN." (PMID 36066972, 2022). "Little was known, however, about the function of MYOF in regulating intracellular ROS production in cancer cells." (PMID 36147922, 2022). "In the ccRCC proteomic dataset, we identified 38 RTKs at a range of variable frequency (6.8–100% of 103 cancers), while myoferlin was expressed in all samples." (PMID 35205843, 2022). "Meanwhile, 19 genes have been found to be coexpressed with MYOF, many of which were cancer-related genes." (PMID 34957301, 2021). "On the whole, these findings imply that YQ456 is a potential therapeutic agent in MYOF‐driven cancers." (PMID 33634965, 2021). "MYOF depletion reversed the invasive morphology of cancer cells, as evidenced by reduced mesenchymal representative proteins (Fibronectin and Vimentin) and increased principal epithelial cell adhesion proteins (E‐cadherin and ZO‐1)." (PMID 33634965, 2021). "Previous studies on MYOF mainly explore its roles in intracellular signaling regulation and mitochondrial metabolism in cancer cells." (PMID 33634965, 2021). "Recent studies have shown that myoferlin is overexpressed in several human cancers and enhances tumor progression by regulating migration, invasion, and tumorigenesis." (PMID 34733798, 2021). "Although controversy lies in the effect of MYOF on cancer cell proliferation, most studies have proved that MYOF knockdown inhibits cancer cell migration and metastasis." (PMID 33634965, 2021). "As a pivotal vesicular trafficking protein, Myoferlin (MYOF) has become an attractive target for cancer therapy." (PMID 33634965, 2021). "Further, multiple cell lines with different expression levels of MYOF were selected from the Cancer Cell Line Encyclopedia database." (PMID 33634965, 2021). "The structure of MYOF is characterized by multiple functional C2 domains, which are related to the proliferative and metastatic behaviors of cancers." (PMID 33634965, 2021). "An overview has demonstrated that all FERLIN genes are modulated in several cancer types, among which MYOFERLIN and FER1L4 genes are more frequently upregulated rather than being downregulated." (PMID 33868788, 2021). "The results showed that the expression levels of MYOF were higher in tumor samples than in healthy samples in most cancers." (PMID 34957301, 2021). "MYOF dysfunction has been demonstrated to be related to proliferation, aggressiveness, and angiogenesis of many cancers." (PMID 34957301, 2021). "The depletion of myoferlin in cancer exosomes significantly modulated exosomal protein load, and reduced the capability to induce HUVEC migration and proliferation." (PMID 34039961, 2021). "The Oncomine database was used to compare the transcription levels of MYOF in cancer and healthy people's samples." (PMID 34957301, 2021). "More and more evidences indicate that MYOF has important significance in clinical diagnosis and targeted cancer therapy." (PMID 34178975, 2021). "Myoferlin expression is increased in a large panel of cancer cells and tumors, where most of the studies described its role in the recycling of membrane receptors (EGFR, IGFR...)." (PMID 32575867, 2020).
cancer (continued). "As a consequence, cells of several cancer types overexpress myoferlin and if this overexpression is knocked-down, decrease invasiveness or slow down proliferation." (PMID 32106631, 2020). "Myoferlin is produced in muscle, heart, lung, airway epithelia, vascular endothelia, placenta, skin, testis and in several cancer tissues." (PMID 32106631, 2020). "Such MYOF-targeting compounds are expected to yield promising therapeutic benefits in the treatment of cancer." (PMID 31828126, 2019). "Although initially discovered in skeletal muscle, MYOF has been found to abound in many other tissues as well as various cancers." (PMID 31828126, 2019). "Far beyond their well-described involvement in physiological membrane fusion, several correlations apparently link ferlins, and most particularly myoferlin, to cancer prognosis." (PMID 31443490, 2019). "It would be of interest to further study the link between mini-myoferlin and KRAS mutated cancers as ERK is a mid-pathway signalling protein in this context." (PMID 31443490, 2019). "The roles of myoferlin in both normal cells and cancer cells are of great significance to provide novel and efficient methods of tumour treatment." (PMID 31475450, 2019). "MYOF drives the progression of cancer in various processes, including surface receptor transportation, endocytosis, exocytosis, intercellular communication, fit mitochondrial structure maintenance and cell metabolism." (PMID 31828126, 2019). "Since different types of cancer cells show distinct patterns of metastatic progression driven by specific chemokine secretion and gene expression, MYOF silencing can result in diverse effects in various cells." (PMID 31477752, 2019). "Intriguingly, beyond a simple alteration, myoferlin, otoferlin and Fer1L4 expressions were negatively correlated with patient survival in some cancer types." (PMID 31443490, 2019). "Contribution of MYOF to cancer cell migration is also OXPHOS-dependent in Pancreatic ductal adenocarcinoma." (PMID 31828126, 2019). "In this review, we summarize recent studies and findings of myoferlin and suggest that myoferlin is a novel potential candidate for clinical diagnosis and targeted cancer therapy." (PMID 31475450, 2019). "In the present article, we reviewed the physiological function of MYOF as well as its role in cancer, thus providing a general understanding for further exploration of this protein." (PMID 31828126, 2019). "It is likely that cancer cells also replicate the role of MYOF to facilitate their progression because they are highly active in membraneassociated events to maintain a malignant phenotype." (PMID 31828126, 2019). "Previously, we have described the high expression of myoferlin in several cancers and its involvement in cancer cell plasma membrane biology such as endocytosis, membrane receptor recycling, exocytosis, and exosome formation." (PMID 30850580, 2019). "Myoferlin functions in the proliferation, invasion and migration of cancer cells through various mechanisms." (PMID 31475450, 2019). "Myoferlin was also detected at a protein level in microvesicles/exosomes derived from several cancer cells including the bladder, colon, ovary, prostate, breast and pancreas, where it plays a role in vesicle fusion with the recipient endothelial cells." (PMID 31443490, 2019). "Recently, myoferlin has roles in various cancers, and current studies suggest that myoferlin is a promising target and biomarker." (PMID 31475450, 2019). "Myoferlin plays an oncogenic role and promotes cancer cell metastasis; thus, it often exhibits a relationship with histological grade or clinical stage of cancers." (PMID 31475450, 2019). "Accumulating evidence show that myoferlin, a member of the ferlin family, is highly expressed in several cancer types, where it acts as a tumour promoter and participates in the metabolic rewiring towards oxidative metabolism." (PMID 30850580, 2019).
cancer (continued). "The evidences suggest that myoferlin, when overexpressed, enhances cancer cell proliferation, migration and metabolism by affecting various aspects of membrane biology." (PMID 31443490, 2019). "In pancreatic ductal carcinoma cell (Panc-1), MYOF silencing decreased cancer cell migration by reducing mitochondrial respiration." (PMID 31477752, 2019). "Most studies on MYOF in human cancer are mainly centred on its oncogenic functions, but little has been known about how MYOF gene expression is regulated." (PMID 31828126, 2019). "Myoferlin, being overexpressed in several cancer types, offers very promising advantages for cancer diagnosis and targeting." (PMID 31443490, 2019). "MYOF has been found to regulate the cellular phenotype and the malignant capacity in various types of cancers." (PMID 31477752, 2019). "Recently, a novel protein, myoferlin is reported to be present in pancreatic and breast cancer cells, described as a common protein in cancer cell releasing exosomes." (PMID 29616188, 2018). "Our further investigation showed that WJ460 binding to MYOF sequestered MYOF from Rab7-positive late endosomes, thereby impairing the proper function of late endosomes and the endosomal system in cancer cells." (PMID 30213946, 2018). "The elevated MYOF contributes to migration and invasion of cancer cells and promotes tumour metastasis and angiogenesis." (PMID 29164766, 2018). "The study unravels the importance of myoferlin in cancer progression and metastases with increased exosomal biogenesis and packaging of nucleic acid cargo to adjacent cells." (PMID 29616188, 2018). "Previous studies reported that MYOF is involved in RTKs' recycling (VEGFR2, e.g.)and MYOF depletion reduced VEGF exocytosis by cancer cells." (PMID 30213946, 2018). "In the continuity of our previous studies aiming at understanding the role of myoferlin in cancer, we have sought to investigate myoferlin in the context of energy metabolism in PDAC." (PMID 29720728, 2018). "In patients with cancer, myoferlin protein hyperexpression has been correlated with poor patient prognosis." (PMID 29179496, 2017). "Using proteomic analysis, we demonstrate for the first time that myoferlin depletion in cancer cells leads to a significantly modulated exosomal protein load." (PMID 27845903, 2016). "In order to further understand the molecular effects of myoferlin-depletion in cancer exosomes, we first tested their ability to fuse with human umbilical vein endothelial cells (HUVEC)." (PMID 27845903, 2016). "Collectively, our findings place myoferlin on the short list of key proteins important for cancer exosome biology." (PMID 27845903, 2016). "Accordingly, we transfected a murine miRNA (miR-298) in cancer cells (in both control and myoferlin depleted condition), purified the exosomes from these cells and then incubated them with HUVEC." (PMID 27845903, 2016). "Beyond this, myoferlin-depleted cancer exosomes also had a significantly reduced ability to induce migration and proliferation of HUVEC." (PMID 27845903, 2016). "Recent studies have shown that in addition to muscle cells, myoferlin is also expressed in endothelial and cancer cells." (PMID 26919244, 2016). "As a first step towards characterizing myoferlin-deficient exosomes we sought to assess the modulation of their quantity and size in MDA-MB-231 and BxPC-3 cancer cells." (PMID 27845903, 2016). "Considering their essential role in cell-to-cell communication, we next sought to assess if cancer-derived and myoferlin-depleted exosomes would have a differential impact on human endothelial cells." (PMID 27845903, 2016). "Strengthened by previous proteomic studies, we prove by Western blotting and electron microscopy that myoferlin is indeed a major component of cancer cells-derived exosomes." (PMID 27845903, 2016). "Recent studies have shown that myoferlin is also expressed in other cell types including endothelial cells and cancer cells." (PMID 26919244, 2016).